PAX2 (paired box 2)
Diseases named in the same sentence as PAX2 in open-access papers (continued):
Sharing a sentence is not in itself a finding about the gene and the disease.
ovarian carcinoma (15 papers, 2006 to 2025). A malignant neoplasm originating from the surface ovarian epithelium. "Taken together, these findings suggest Pax2 loss is an early molecular event in ovarian cancer progression that predisposes cells to further mutations that can drive tumorigenesis, regardless of cell of origin." (PMID 30096791, 2018). "In this study, we demonstrated that knockdown PAX2 expression in ovarian cancer cells with high level of PAX2 expression is associated with reduced cell proliferation and motility." (PMID 23502471, 2013). "Interestingly, cells lost Pax2 expression in a fallopian tube model of ovarian cancer derived through loss of Pten." (PMID 30096791, 2018). "Conversely, PAX2 overexpression is associated with cystic or tumorous epithelial overgrowth, such as renal cystic dysplasia, renal cell carcinoma, Wilms’ tumor, nephrogenic adenoma, prostate cancer, breast cancer and ovarian cancer." (PMID 23502471, 2013). "Taken together, these data suggest that loss of PTEN induces reprogramming of the FTE cells into a more stem-like phenotype due to loss of PAX2 and provides a model to study early events during the FTE-driven ovarian cancer tumor formation." (PMID 33828085, 2021). "This study gives new insight into the origins of FTE-derived ovarian cancer tumor cell heterogeneity due to loss of PTEN and PAX2, providing a model to study the mechanisms responsible for the emergence of cancer stem cells." (PMID 33828085, 2021). "MiRNA-375 represses the growth, drug sensitivity and metastasis of ovarian carcinoma cell by targeting Paired Box 2 (PAX2)." (PMID 32782028, 2020). "Further studies are needed to precisely define signaling changes induced by PAX2 that contribute to the biology of oviductal cells and the transition to SCOUTs, STICs and early ovarian cancer." (PMID 29100356, 2017). "RPPA was used to analyze the effects of PAX2 knockdown on the expression of 207 signaling proteins in ovarian cancer cell lines RMUGL and TOV21G." (PMID 23502471, 2013). "Further investigation of the roles of these up-regulated genes in PAX2 knockdown cells will be necessary to clarify their potential tumor suppression function in PAX2-expressing ovarian cancer cells." (PMID 23502471, 2013). "Twenty-six ovarian cancer cell lines with different histology origins were screened for PAX2 expression." (PMID 23502471, 2013). "On the other hand, we have also shown for the first time that over-expressing PAX2 in PAX2-negative ovarian cancer cell lines suppresses their cell proliferation." (PMID 23502471, 2013). "Wound healing assays showed that PAX2 knockdown ovarian cancer cell lines had decreased cell motility in comparison to the parental PAX2-expressing cell lines." (PMID 23502471, 2013). "The potential oncogenic role of PAX2 in these ovarian cancer cells is consistent with previous findings in prostate cancer, colon cancer, breast cancer and renal cancer." (PMID 23502471, 2013). "In conclusion, understanding PAX2’s and PAX8’s distinct roles in ovarian tumorigenesis helps refine diagnostic and prognostic strategies and offers potential avenues for developing targeted therapies to treat ovarian cancer more effectively." (PMID 40506992, 2025).
ovarian carcinoma (continued). "However, in contrast to ovarian cancer where PAX2 expression is reduced in SCOUTs, the high levels of PAX2 expression observed in metastatic sites of CC-RCC seem to contradict the notion that decreased PAX2 expression is associated with EMT in CC-RCC." (PMID 29928489, 2018). "However, in contrast, PAX2 is expressed in several cancer types, including kidney, prostate, breast, and ovarian cancer." (PMID 29928489, 2018). "In summary, PAX2 could have both oncogenic and tumor suppression functions, which might depend on the genetic content of the ovarian cancer cells." (PMID 23502471, 2013). "In summary, PAX2 could have both oncogenic or tumor suppression functions, which will depend on the genetic content of ovarian cancer cells." (PMID 23502471, 2013). "Thus, the increased expression of Annexin A1 supports the notion that PAX2 may promote tumor growth in TOV21G ovarian cancer cell line by inhibiting the early stages of apoptosis through down-regulation of Annexin A1." (PMID 23502471, 2013). "However, over-expressing PAX2 in PAX2-negative ovarian cancer cells suppressed their growth." (PMID 23502471, 2013). "The function of PAX2 in the development of ovarian cancer is still unknown." (PMID 23502471, 2013). "It was suggested that PAX2 and PAX5 play tumor suppressor roles in ovarian cancer and leukemia, while conversely, PAX3, PAX7, and PAX6 were reported to be oncogenic in embryonal rhabdomyosarcomas and retinoblastoma." (PMID 31235851, 2019). "Studying PAX2 and PAX8 in this context provides valuable insight into the site of origin of ovarian cancer and the tumorigenic properties that make the PAX proteins promising drug targets for treatment of HGSC." (PMID 30096791, 2018). "Two ovarian cancer cell lines: RMUGL (mucinous) and TOV21G (clear cell), with high PAX2 expression were chosen for further study." (PMID 23502471, 2013). "In this review, we examine the implications of PAX2 and PAX8 expression in the cell of origin of serous cancer and their potential efficacy as drug targets by summarizing their role in the molecular pathogenesis of ovarian cancer." (PMID 30096791, 2018). "This is consistent with the PAX2 expression in non-serous ovarian cancer from the gene expression data of ovarian cancer patient samples with different histological subtypes (GSE6008) and our own microarray data." (PMID 23502471, 2013). "In this study, using both PAX2 positive and negative ovarian cancer cell lines, we investigated the potential functional roles of PAX2 in ovarian cancer." (PMID 23502471, 2013). "In this study, we found that PAX2 is frequently expressed in ovarian cancer cell lines, especially for those derived from non-serous type ovarian cancers (clear cell, mucinous, and endometrioid)." (PMID 23502471, 2013). "Due to the fact that WT1 gene has been shown to be transcriptionally regulated by some upstream transcriptional factors like Sp1, PAX2, PAX8 and PEA3, it is worthwhile to further analyze the expression status of these upstream molecules in ovarian cancer specimens obtained from this population." (PMID 16606472, 2006). "Since PAX2 and PAX8 are expressed in the fallopian tube, and PAX8 expression is maintained in HGSC, the expression and regulation of PAX proteins may help to explain the source of ovarian cancer." (PMID 30096791, 2018). "However, the functional role of PAX2 in ovarian cancer is not known." (PMID 23502471, 2013). "A recent publication has shown that ovarian cancer cells in suspension acquire an EMT phenotype, so it is possible that inducing an EMT phenotype in the OVE cells enhanced their ability to proliferate in suspension and that this action is independent of any effects on PAX2." (PMID 29100356, 2017).
renal hypoplasia (15 papers, 2007 to 2025). Renal hypoplasia is a developmental anomaly in which one or both kidneys (unilateral or bilateral renal hypoplasia, respectively) have a deficit in the number of nephrons and may be small. "Heterozygous variants in the PAX2 gene were first described as the cause of the syndrome in 1995 in a family with renal hypoplasia and optic nerve colobomas." (PMID 40282888, 2025). "Studies have suggested that PAX2 mutations associated with renal hypoplasia almost invariably progress to ESKD." (PMID 40948392, 2025). "A different study that was conducted on 29 Brazilian kindreds who had the same PAX2 mutation confirmed that renal hypoplasia was the most prevalent congenital defect in these patients." (PMID 37628926, 2023). "The LMX1B variant was de novo, whereas the PAX2 variant was inherited from the mother, who had bilateral renal hypoplasia and mild chronic kidney disease." (PMID 36835576, 2023). "According to the fact that patients with the PAX2 mutation associated with renal hypoplasia will develop ESRD in almost 100% of cases, it is crucial for all children presenting severe kidney malformations associated with ESRD to be tested for this mutation." (PMID 37628926, 2023). "PAX2 gene mutations were reported to be associated with isolated kidney diseases, such as renal hypoplasia or dysplasia, in cases with kidney and urinary tract malformations and no ocular abnormalities." (PMID 37628926, 2023). "Although PAX2 mutations have a higher frequency in patients with PAPRS or non-syndromic renal hypoplasia, from the review of variants reported to date in LOVD3, PAX2-related disorders are detected in pediatric patients with other CAKUT phenotypes." (PMID 36835576, 2023). "The same study was continued in mice to determine in what manner the PAX2 mutation causes renal hypoplasia." (PMID 37628926, 2023). "Patients with the PAX2 mutation associated with renal hypoplasia will develop end-stage renal disease (ESRD) in almost 100% of cases; therefore, patients with severe kidney malformations associated with ESRD should be tested for mutations of this gene." (PMID 37628926, 2023). "Recent studies have shown that PAX2 gene plays critical roles in organogenesis during embryonic development, and the PAX2 mutation is the most common cause of renal hypoplasia." (PMID 30241513, 2018). "In 1995, the first gene defect described as being causative of CAKUT was a frameshift deletion in PAX2 in a family with optic nerve coloboma, renal hypoplasia and vesicoureteral reflux." (PMID 28398236, 2017). "Studies into cases of ‘non-syndromic’ renal hypoplasia have identified mutations in several key genes which include PAX2, SIX2, BNP4, SALL1, UMOD and TCF2." (PMID 24886545, 2014). "Phenotypic variability has been observed not only with differing mutations, but also with the same mutation and within the same family, and PAX2 mutations have also been reported in isolated renal hypoplasia and in VUR." (PMID 17216254, 2007). "Similarly, while common hypomorphic variants of RET or PAX2 have been associated with subtle renal hypoplasia, their inactivation has been shown to result in severe renal malformations." (PMID 29240767, 2017). "Kidney disorders associated with PAX2 variants involve CAKUT, renal interstitial fibrosis, renal hypoplasia, cystic disorders, nephrotic syndrome, and urogenital cancers." (PMID 40282888, 2025). "The PAX2-related disorder is characterized by autosomal dominant inheritance and, almost invariably, by renal hypoplasia, progressive renal failure in childhood, and optic nerve colobomas." (PMID 38139322, 2023). "A frameshift deletion of PAX2 in a family with optic nerve colobomas, renal hypoplasia and VUR represents the first reported single gene defect causation of congenital anomalies of the kidney and urinary tract (CAKUT)." (PMID 32776440, 2020).
renal hypoplasia (continued). "The human probands we identified presented with renal hypoplasia, which could be a result of impaired renal tubule development/branching morphogenesis defect during renal development to which reduced Pax2 expression could contribute." (PMID 38154558, 2024). "The results suggested that PAX2 haploinsufficiency may directly lead to renal hypoplasia." (PMID 37628926, 2023). "On the other extreme, absence of a single PAX2 allele will cause renal hypoplasia." (PMID 21689023, 2011).
breast carcinoma (14 papers, 2011 to 2023). "Overall, our findings were supporting the idea that PAX2–Tam induces massive transcription of genes that promotes cell death in breast cancer patients and that the loss of their expression is associated with resistance to Tam." (PMID 32843722, 2020). "Moreover, it has been described that high level of PAX2 is associated with better survival in Tam treated ER+ breast cancer patients." (PMID 32843722, 2020). "The results of this work have demonstrated that PAX2 induces the transcription of genes key for the initiation of apoptosis in ER+/HER2− breast cancer cells." (PMID 32843722, 2020). "Previously, we and others reported that paired box 2 protein (PAX2) is a key factor in breast cancer by repressing the transcription of ERBB2/HER2 in ER-positive (ER+) breast cancer." (PMID 32843722, 2020). "In this study, we have characterized the role of PAX2 in ER+/HER2− breast cancer cells, specifically under conditions where ER has been inhibited with an antagonist." (PMID 32843722, 2020). "The degree of cell growth inhibition correlated with PAX2 expression levels, confirming the previous data implicating PAX2 as a repressor in breast cancer." (PMID 32843722, 2020). "The role of PAX2 regulating the transcription of ERBB2/HER2 in breast cancer was previously reported in ER+ cells treated with Tam." (PMID 32843722, 2020). "It has been also reported that PAX2 is activated by E2 via ERα in breast cancer and it is confirmed that the expression of PAX2 is proportional to the expression of ERα in ovarian serous cancer." (PMID 32512900, 2020). "The co-enrichment of PAX2 sites with ERα binding is consistent with a recognized role for PAX2 in human breast cancer cells." (PMID 31408468, 2019). "PAX2 was shown to be expressed in a subset of breast cancers and was recruited to the ER binding site after both estrogen and tamoxifen treatment." (PMID 31408468, 2019). "This event has also been shown in tamoxifen-treated breast cancer samples, where the PAX2-positive AIB-1-negative tumors have the best prognosis and the lowest percentage of ERBB2-positive cells." (PMID 23192763, 2013). "To characterize PAX2 regulation in breast cancer cells, we first compared basal expression and activation of PAX2 between luminal and non-luminal cell lines." (PMID 22168360, 2011). "The objective of the present study was to investigate a putative role for PAX2 in the control of luminal breast cancer cells invasion, and to begin to characterize its regulation." (PMID 22168360, 2011). "Collectively, these results indicate that PAX2 activation in response to estradiol is selectively achieved in breast cancer cells of the luminal subtype." (PMID 22168360, 2011). "We show here that PAX2 protein is activated by estradiol, in breast cancer cells of the luminal subtype only, in agreement with clinical data showing preferential activation of PAX2 in tumours of the luminal subgroup in vivo." (PMID 22168360, 2011). "Further, it reveals a new role for PAX2 in the maintenance of a low invasive behavior in luminal breast cancer cells upon exposure to estradiol, and shows that overexpression and activation of PAX2 in these cells is sufficient to reduce their invasive ability." (PMID 22168360, 2011). "In the present study, we describe a new role for PAX2 in luminal breast cancer cells, as a negative regulator of cell invasiveness." (PMID 22168360, 2011). "Considering such a key role for PAX2 in the control of luminal breast cancer cell invasiveness, understanding the mechanisms regulating its activity is primordial." (PMID 22168360, 2011). "Accordingly, we speculated that EZH2 might cooperate with PAX2 in breast cancer, which needs to be further investigated." (PMID 36318256, 2023). "Considering that IRF1 is an important transcription factor mediating apoptosis in breast cancer, we hypothesized that the induction of genes related to growth arrest and cell death by PAX2 could be partially attributed to IRF1 upregulation." (PMID 32843722, 2020).